TLR4 (toll like receptor 4)
Diseases named in the same sentence as TLR4 in open-access papers (continued):
Sharing a sentence is not in itself a finding about the gene and the disease.
Parkinson disease (77 papers, 2009 to 2026). A progressive degenerative disorder of the central nervous system characterized by loss of dopamine producing neurons in the substantia nigra and the presence of Lewy bodies in the substantia nigra and locus coeruleus. "While TLR4 has been implicated in movement disorders such as Parkinson’s disease and amyotrophic lateral sclerosis, pathogenic effects were associated with neuroinflammation through activation of microglia." (PMID 39147737, 2024). "Studies in animal models of Parkinson’s disease have also found that activation of the Toll-like receptor 4/TNF receptor-associated factor 6 (TRAF6)-mediated MAPK signaling pathway is involved in neuroinflammatory processes." (PMID 37207228, 2023). "Toll-like receptor 4 deficiency has been found to significantly attenuate the activation of the Toll-like receptor 4/NF-κB signaling pathway in the midbrain of MPTP-induced Parkinson’s disease mice and reduce neuroinflammation." (PMID 37207228, 2023). "Of course, the inflammatory pathological process that relies on α-synuclein Toll-like receptor 4 activations may also be an early cause of Parkinson’s disease." (PMID 37207228, 2023). "Further evidence is emerging for a possible role of the adaptive immune in the development of Parkinson's disease as toll‐like receptor 4 (TLR4) gene polymorphisms have been linked to sporadic Parkinson's disease and α‐synuclein can induce the up‐regulation of TLRs." (PMID 26511587, 2016). "Thus, early gut dysfunction signaling pathways caused by Toll-like receptor 2 and Toll-like receptor 4 destructions may directly lead to elevated α-synuclein levels and aggregation in prodromal Parkinson’s diseases." (PMID 37207228, 2023). "However, targeting Toll-like receptor 2 and Toll-like receptor 4 may have diagnostic potential to predict patients at risk of Parkinson’s disease or to stratify disease progression." (PMID 37207228, 2023). "Therefore, Toll-like receptor 2 and Toll-like receptor 4 are potential targets to develop new therapies to alter the course of disease in people at high risk of Parkinson’s disease and improve gut disorders in patients in the prodromal phase or with established disease." (PMID 37207228, 2023). "In pathological conditions, amyloid-β (Aβ) and tau (key players in Alzheimer’s’ disease (AD)) induce TLR4 activation, while α-synuclein (a key player in Parkinson’s disease (PD)) induces TLR2 and TLR5 activation." (PMID 41280719, 2025). "A recent study demonstrated that in Parkinson’s disease, SB improves brain function by inhibiting microglia-mediated neuroinflammation by TLR4/MyD88/NF-κB signaling pathway." (PMID 39962509, 2025). "The entry of these bacterial components into the brain can activate Toll-like receptor 4, contributing to chronic neuroinflammation and potentially accelerating the progression of conditions such as Alzheimer’s and Parkinson’s." (PMID 39942791, 2025). "Studies have also found that blocking the TLR4 pathway can improve motor function and prevent the death of dopaminergic neurons in mouse models of Parkinson’s disease." (PMID 38892278, 2024). "As the research continues, Ali Keshavarzian published ‘Role of TLR4 in the gut-brain axis in Parkinson’s disease: a translational study from men to mice’ in the Gut in 2019 has only 298 citations." (PMID 39403202, 2024). "We performed cell and animal experiments to explore the therapeutic effect of artemisinin on Parkinson's disease (PD) and the TLR4/Myd88 signaling pathway." (PMID 36691817, 2023). "Autopsy of Parkinson’s disease patients has seen an increased expression of Toll-like receptor 4 in the substantia nigra of the midbrain." (PMID 37207228, 2023). "Patients with Parkinson’s disease exhibit elevated levels of Toll-like receptor 4 protein and putamen samples in colon biopsies, circulating monocytes, and postmortem caudate nucleates." (PMID 37207228, 2023).
Parkinson disease (continued). "We reviewed the latest evidence that disrupted Toll-like receptor 2 or Toll-like receptor 4 signaling pathway leads to Parkinson’s disease in gut homeostasis and enteric nervous system, as well as gut dysfunction in Parkinson’s disease." (PMID 37207228, 2023). "In Parkinson’s disease, TLR4-NFκB pathway activation and potassium outflow both promoted pyroptosis of neuronal cells." (PMID 35165294, 2022). "Fecal microbiota transplantation (FMT) protects Parkinson's disease model mice by inhibiting neuroinflammation and reducing Toll-like receptor 4/Tumor necrosis factor-alpha (TLR4/TNF-α) signaling." (PMID 34589510, 2021). "Another genus that expanded in the TLR4-KO mice, Papillibacter, has been shown to decrease in patients with Parkinson’s disease with increased TLR4 expression." (PMID 34884634, 2021). "Activation of the TLR4/PI3K/AKT/GSK3β signaling pathway in macrophages/microglia aggravated neuroinflammation in Parkinson’s disease." (PMID 32826878, 2020). "The important role of TLR4 in the inflammatory response was also evaluated using MPTP as an inducer of Parkinson-like lesion in mouse." (PMID 30618635, 2018). "The upregulation of TLR-4 expression has been reported in Parkinson’s disease and multiple systems atrophy post-mortem brain tissue, suggesting clinical relevance of TLR-4 in the progression of many widespread neurodegenerative diseases." (PMID 30260985, 2018). "Studies have shown that Trem2 can inhibit TLR4‐mediated NF‐κB activation in Parkinson's disease." (PMID 40205810, 2025). "Transplanting beneficial bacteria colonies into Parkinson’s disease mice could protect these mice through inhibiting neuroinflammation and reducing TLR4/TNF-α signaling." (PMID 41195080, 2025). "While Toll-like receptor 2 and Toll-like receptor 4 in Toll-like receptors are important sub-receptors for inducing Parkinson’s disease development, Toll-like receptor 2 and Toll-like receptor 4 are generally expressed in a healthy gut but are more obvious in the colon." (PMID 37207228, 2023). "Parkinson's patients also have enhanced expression of TLR4 in circulating monocytes and B cells." (PMID 36788995, 2023). "Although the exact mechanism of Parkinson’s disease pathogenesis is unknown, in the activation of Toll-like receptor, primarily Toll-like receptor 4 and subsequent neuroinflammation, the immune response appears to play an important role." (PMID 37207228, 2023). "We suspect that Toll-like receptor 2 and Toll-like receptor 4 signaling pathways may promote Parkinson’s disease pathogenesis by increasing gut permeability and gut inflammation, thereby driving α-synuclein aggregation in the gut or brain." (PMID 37207228, 2023). "In another study, the development of PD-associated neuroinflammation was reduced in TLR-4-deficient Parkinson’s disease (PD) mouse models compared with normal mice without PD." (PMID 35978950, 2022). "TLR4-mediated inflammation may also be one of the key factors leading to neurodegeneration in Parkinson's disease." (PMID 36523959, 2022). "Conversely, a reduction in dopamine release, which occurs during the early stage of Parkinson disease, may negatively modulate TLR4-mediated neurotoxic microglia and neuroprotective astrocyte function." (PMID 35052674, 2022). "This hypothesis is further supported by the pronounced reduction in neuroinflammation in a rodent model of Parkinson’s disease following TLR4 ablation." (PMID 34838047, 2021). "Endogenous TLR4 expression is thought to be neuroprotective in some contexts; for example, by mediating microglial autophagy of neurotoxic plaques in primary mouse microglia and experimental rat models of Parkinson’s disease." (PMID 34838047, 2021). "Additionally, there is evidence that TLR2 and TLR4 play a role in Parkinson ́s disease through microglia activation." (PMID 33499143, 2021).
Parkinson disease (continued). "Additionally, RA inhibited NF-κB nuclear expressions and downregulated the HMGB1, Myd88, and TLR4 expressions in cell and animal models of Parkinson’s disease." (PMID 34827094, 2021). "Moreover, previous studies showed that inhibiting the TLR4 pathway alleviated motor impairment and dopaminergic neuron death in the Parkinson's disease mouse model." (PMID 34777683, 2021). "Moreover, increased TLR4 expression has been detected in the substantia nigra of patients with Parkinson’s disease, and in a mouse model of amyotrophic lateral sclerosis." (PMID 34838047, 2021). "In addition, agents effective in blocking HMGB1/TLR4/NF-κB signaling have proven protective in animal models of Parkinson’s disease and could be useful in the treatment of AUD." (PMID 37626919, 2023). "Notably, Toll-like receptor 2 and Toll-like receptor 4 are dysregulated in Parkinson’s disease patients and may therefore be identified as the core of early gut dysfunction in Parkinson’s disease." (PMID 37207228, 2023). "However, targeting Toll-like receptor 2 and Toll-like receptor 4 in the gut may exert multiple benefits when administered alone or in combination with current Parkinson’s disease therapies." (PMID 37207228, 2023). "It has been shown that the TLR4/myeloid differentiation primary response 88 (MyD88)/nuclear factor (NF‐kB) signalling pathway mediates neuroinflammation in CNS diseases such as Alzheimer's disease (AD), Parkinson's disease (PD), subarachnoid haemorrhage (SAM) and vascular dementia." (PMID 35393774, 2022). "For instance, extracellular α-syn oligomers and fibrils produced during the course of Parkinson disease (PD) bind to TLR4 and TLR2 expressed on microglia." (PMID 35563729, 2022). "Microglia-mediated neuroinflammation may play an important role in the initiation and progression of dopaminergic (DA) neurodegeneration in Parkinson's disease (PD), and TLR4 induced by the prothrombin kringle-2 plays an essential role in the activation of microglia in the adult brain." (PMID 32479555, 2020). "Microglia-mediated neuroinflammation may play an important role in the initiation and progression of dopaminergic (DA) neurodegeneration in Parkinson’s disease (PD), and toll-like receptor 4 (TLR4) is essential for the activation of microglia in the adult brain." (PMID 26440368, 2015). "In a Parkinson's disease mouse model, paquinimod treatment downregulated the expression of inflammatory cytokines (IL‐6, IL‐1β and TNF‐α) and suppressed the TLR4/NF‐κB signalling pathway." (PMID 41582634, 2026). "Guided by these results, a scoping review of the literature was undertaken to summarize existing evidence addressing TLR4-dependent mechanisms in MASLD and Parkinson's disease." (PMID 41874031, 2026). "The aim of our study was to delineate TLR4-mediated immune networks underpinning the molecular overlap between MASLD and Parkinson's disease." (PMID 41874031, 2026). "In α-syn contexts relevant to Parkinson’s disease, HXT reduces the TLR4/MyD88 cascade that drives NF-κB/MAPK signalling and NLRP3 inflammasome activation, a central pathogenic axis produced during Parkinson’s disease." (PMID 41227598, 2025). "In addition, TLR4 displays an important role in the central nervous system by mediating the activation of the inflammatory nuclear factor-κB (NF-κB), as documented in several neurodegenerative diseases such as Alzheimer’s, Parkinson’s, Huntington’s diseases, and Amyotrophic Lateral Sclerosis." (PMID 39519164, 2024). "In Parkinson’s disease, FMT was shown to inhibit the expression of TLR4 and NF-κB." (PMID 38449863, 2024). "The function of SCFA in Parkinson’s disease may be related to CD3+ T cells, TLR4+ cells, and depend on the gut-brain axis." (PMID 37388445, 2023).
Parkinson disease (continued). "Therefore, Toll-like receptor 2 and Toll-like receptor 4 are likely to affect candidates for leaky gut and inflammatory responses, intestinal denervation, and early colonic motility disorders, all of which may help explore the pathogenesis of Parkinson’s disease." (PMID 37207228, 2023). "In contrast with observations in AD, Parkinson’s disease, andamyotrophic lateral sclerosis patients,Tlr4 mRNA was not upregulated inTpp1–/– brains, which argues for a unique pathway ofmicroglia activation in this model." (PMID 31003587, 2019). "Parkinson’s disease is no exception, and the Toll-like receptor 4 signaling pathway involves multiple pathways in pathogenesis studies, starting with the classical Toll-like receptor 4/NF-κB signaling pathway, which is involved in the immune inflammatory response." (PMID 37207228, 2023).
tuberculosis (77 papers, 2007 to 2026). A chronic, recurrent infection caused by the bacterium Mycobacterium tuberculosis. "TLR4 stimulation has been shown to be associated with reduced odds of tuberculosis relapse in ART-treated patients." (PMID 39339847, 2024). "Research has shown that rs10759932 polymorphisms in the TLR4 are associated with different inflammatory diseases, such as chronic obstructive pneumonia, tuberculosis, and other diseases." (PMID 38652726, 2024). "After adjustment for tuberculosis status, the rs4986790-G (TLR4) and rs5743551-G (TLR1) alleles were significantly associated with the changes in CD4+ cell count above/below 200 cells/mm3." (PMID 37606452, 2023). "The TLR4 rs4986790 polymorphism is a risk factor for active tuberculosis in Caucasian HIV-infected patients." (PMID 37606452, 2023). "Polymorphisms in the TLR2 and TLR4 genes are mostly associated with a susceptibility to tuberculosis." (PMID 36611413, 2022). "TLR4 is a critical component of the immune response against tuberculosis; its genetic polymorphisms have been linked to latent or active M.tb infection." (PMID 34632719, 2021). "The minor allele (G) of rs4986790 in TLR4 (D299G) decreased the risk of active tuberculosis in the allelic (A vs. G, OR = 0.31, 95%CI = 0.09‐0.81, p = 0.01) and in the dominant genetic model (AA vs. GG+AG, OR = 0.26, 95%CI = 0.09‐0.77, p = 0.02)." (PMID 32411792, 2020). "It has been reported that people with TLR4-rs2737190-A/G genotype had a higher risk of clinical tuberculosis or smear-positive tuberculosis." (PMID 33138336, 2020). "The polymorphism rs352139, located in the intronic region of TLR4, has been demonstrated to be associated with the susceptibility to tuberculosis in Indonesian females." (PMID 31328431, 2019). "The SNP ofrs12377632 where is the promoter of the TLR4 gene located near 9q33.1 (precise position:120465144), Closely related to susceptibility to tuberculosis in our study." (PMID 29348888, 2017). "People with haplotype TLR4 rs10983755G–rs10759932C had a significantly increased risk of tuberculosis (OR: 3.43, 95% CI: 2.34–5.05)." (PMID 27339100, 2016). "Haplotype analysis found an increased risk for tuberculosis among individuals carrying TLR4 rs10983755G–rs10759932C." (PMID 27339100, 2016). "High TLR2 and TLR4 expression during anti-tuberculosis treatment associated with a moderate form of disease suggests that these receptors were seems likely beneficial to the patients because such TLRs can induce the production of pro-inflammatory cytokines." (PMID 24558401, 2014). "And among blacks, a combination of SNPs in TNF-α and TLR4 predicted tuberculosis risk with 71% accuracy." (PMID 20196868, 2010). "In this study, Lactobacillus casei attenuated oxidative stress in the liver, repaired the intestinal barrier, regulated intestinal flora, alleviated LPS release into the blood, and modulated the TLR4–NF-κB–MyD88 pathway to attenuate liver injury caused by anti-tuberculosis drugs." (PMID 37298396, 2023). "Thus, previous studies have revealed the association between TLR4 and bacterial-related phenotypes, including tuberculosis, cirrhosis, ascites, scrub typhus and Crohn’s disease." (PMID 33396586, 2020). "Moreover, ATT treatment has been shown to increase the expression of TLR2 and TLR4 in tuberculosis, indicating their association with disease protection." (PMID 30218032, 2018). "rs7696323 is located in the intron of the TLR2 gene located near 4q31.3 (precise position: 154605745) and rs11536889 is located in the 5’UTR of the TLR4 gene located near 9q33.1 (precise position: 120478131)has nothing to do with susceptibility of tuberculosis in Chinese Han children." (PMID 29348888, 2017). "Our results suggest that genetic polymorphisms of IL-17 and TLR4 may play a role in host susceptibility to tuberculosis in the Chinese Han population." (PMID 27339100, 2016).